ENSG00000291315 (novel protein)
Gene: Protein-coding gene on chromosome 3 (40,312,086 to 40,312,214, forward strand). Ensembl gene ENSG00000291315.
Homologues: Orthologues: mouse Gm64043 (79% identical).